FGF21 (fibroblast growth factor 21)
Diseases named in the same sentence as FGF21 in open-access papers (continued):
Sharing a sentence is not in itself a finding about the gene and the disease.
Genetic obesity (3 papers, 2021 to 2023). "The relevance of this study is due to the fact that mutational disorders of MC4R signaling are the most common form of genetic obesity in humans, but the effect of FGF21 on metabolic disorders caused by a decrease in MC4R functions has been little studied." (PMID 34943946, 2021). "Wedemonstrated earlier that FGF21 increases locomotor activityequally in male and female Ay mice with genetic obesity." (PMID 37469453, 2023). "The therapeutic effects of FGF21 were observed in mice with both diet-induced and genetic obesity caused by the absence of leptin (ob/ob) or its functional receptor (db/db)." (PMID 34943946, 2021).
gout (3 papers, 2023 to 2025). A condition characterized by painful swelling of the joints, which is caused by deposition of urate crystals. "Prospective pharmacovigilance studies should evaluate whether concomitant administration of NLRP3 inhibitors (e.g., colchicine) or IL-1β-neutralizing biologics could mitigate FGF21-associated gout flare risk in predisposed individuals." (PMID 40388724, 2025). "The most significantly upregulated protein in the hyperuricemic gout samples compared to normouricemic gout was the hepatokine FGF-21, which also correlated with sUA concentrations (r = 0.29, p < 0.0001)." (PMID 37810213, 2023). "Our study indicates that rhFGF-21 dampened cytokine production and we hypothesize that FGF-21 may play a role in limiting gouty inflammation by decreasing the inflammatory response of the gout-specific stimulus, C16.0 and MSU." (PMID 37810213, 2023). "While the mechanisms of bone erosion in gout are incompletely understood, most studies point toward the implication of the RANKL/OPG pathway dysregulation, which may present a limitation to the potential use of FGF-21 in gouty arthritis." (PMID 37810213, 2023). "We hypothesized that FGF-21 may be an adaptive regulator in hyperuricemia and gout-related inflammation." (PMID 37810213, 2023). "Even though FGF-21 analogs are currently undergoing clinical trials and that FGF-21 has emerged as a viable therapeutic target for metabolic disorders, particular consideration should be given to reported side effects in relation to a potential use in gouty arthritis." (PMID 37810213, 2023). "Our findings suggest that elevated levels of FGF21, MMP-1, G-CSF, and IFN-γ are positively correlated with the onset of gout, as indicated by the forward MR analysis." (PMID 40388724, 2025). "We found two proteins FGF-21 and CCL25 significantly overexpressed in HU patients with gout compared to NU gout and another 8 nominally significant." (PMID 37810213, 2023). "The analysis results indicate that FGF-21, MMP-1, G-CSF, and IFN-γ are involved in the pathogenesis of gout, and gout may influence the expression of CXCL1, IL-1Ra, and TNF-α." (PMID 40388724, 2025). "Specifically, we identified multiple CIPs, including FGF21, MMP-1, G-CSF, IFN-γ, CXCL1, IL-1Ra, and TNF-α, which may serve as potential molecular therapeutic targets for gout." (PMID 40388724, 2025).
Hashimoto thyroiditis (3 papers, 2021 to 2024). An autoimmune disorder caused by the production of autoantibodies against thyroid tissue. "This study aimed to measure FGF-21 serum levels in children and adolescents with Hashimoto’s thyroiditis and investigate any possible associations between FGF-21 serum levels and resting metabolic rate (RMR) and levothyroxine (LT4) treatment, or other clinical and biochemical parameters." (PMID 34946319, 2021). "We aimed to investigate serum FGF21 level and its relation to thyroid hormones and metabolic parameters among patients with Hashimoto’s thyroiditis (HT)." (PMID 39452947, 2024). "We investigated the association among FGF-21 levels, resting metabolic rate (RMR), and l-thyroxin (LT4) treatment in children and adolescents with Hashimoto’s thyroiditis." (PMID 34946319, 2021). "Therefore, the aim of our study was to evaluate the relationship between FGF21, thyroid hormone levels, and metabolic parameters among adult patients treated with Hashimoto’s thyroiditis." (PMID 39452947, 2024).
hypertensive heart disease (3 papers, 2021 to 2023). Abnormal enlargement of the heart resulting from long-standing hypertension. "The association between Fgf21 and some cardiovascular diseases, such as myocardial infarction, hypertensive heart disease, and cardiac hypertrophy has been intensely investigated." (PMID 34708083, 2021). "During HP, both systemic and cardiac FGF21 will be induced and act on the heart to avoid hypertensive heart disease." (PMID 37424900, 2023). "A more recent study suggested that Fgf21 enables the prevention or reverse the cardiac fibrosis in a mouse model with hypertensive heart disease." (PMID 34708083, 2021).
hyperuricemia (3 papers, 2023 to 2024). An abnormally high level of uric acid. "We found that the relative mRNA levels of hepatic FGF21 was lower by 31% in the hyperuricemia mice than that in the control, demonstrating that the over-expression of CYP7A1 in the liver was linked to a glucocorticoid disorder." (PMID 38034015, 2023).
insomnia (3 papers, 2020 to 2025). A sleep disorder characterized by difficulty in falling asleep and/or remaining asleep. "Lower levels of irisin, BDNF and meteorin, and higher levels of FGF-21 and interleukins 6 and 10, lead to sleep disturbances, like insomnia, reduction of REM (rapid eye movement) sleep time and lower slow-wave activity during the NREM (non-rapid eye movement) sleep phase." (PMID 41010737, 2025). "We have measured for the first time three of the most studied mitokines (FGF21, GDF15 and HN) in the framework of insomnia." (PMID 32420904, 2020).
liver failure (3 papers, 2022 to 2025). A liver disease characterized by the liver losing or has lost all of its function. "As a stress-induced hormone, the potential of FGF21 to act as a therapeutic target in the treatment of liver failure has been studied, but the beneficial effects of FGF21 on cholestasis is barely known." (PMID 39040469, 2024). "Potential indicators of cysteine’s influence may encompass growth differentiation factor 15 (GDF15), FGF21, blood cysteine levels, and the resolution of lactatemia and liver failure." (PMID 40430469, 2025). "The FGF21 played a protective role in liver failure in a Kunming mice model induced by D-galactose." (PMID 36440004, 2022). "Currently, few studies have examined FGF21’s role in liver failure." (PMID 36440004, 2022). "All these data suggested a fact that FGF21 had an important role in liver failure, but the exact mechanism of FGF21 in ACLF has not been engaged deeply, and the clinical utility also needs further systemic investigation." (PMID 36440004, 2022). "Although these data indicate that FGF21 could act as a therapeutic target in the treatment of liver failure, the beneficial effects of FGF21 have not been assessed under cholestasis conditions." (PMID 39040469, 2024).
MERRF (3 papers, 2020 to 2023). A mitochondrial encephalomyopathy characterized clinically by a mixed seizure disorder, myoclonus, progressive ataxia, spasticity, and a mild myopathy. "Concordantly, two chemokines related to the mtUPR and the mitochondrial integrated stress response (mtISR), FGF21 and GDF-15, have been found increased in serum samples from MERRF patients." (PMID 35922766, 2022).
mitochondrial encephalomyopathy (3 papers, 2020 to 2024). A heterogenous group of disorders characterized by alterations of mitochondrial metabolism that result in muscle and nervous system dysfunction. "Genetic sequencing is the gold standard for diagnosing mitochondrial encephalomyopathies, preceded by non-invasive tests such as fibroblast growth factor-21 and growth differentiation factor-15." (PMID 38391710, 2024).
peripheral vascular disease (3 papers, 2015 to 2019). Any disorder affecting blood flow through the veins or arteries outside of the heart. "Further studies revealing the immanent connection of FGF21 with the pathology of diabetic peripheral vascular disorders may provide a new prospective strategy for LEAD." (PMID 25850006, 2015).
pheochromocytoma (3 papers, 2019 to 2021). "Human WAT expresses negligible amounts of FGF21 mRNA, while human perirenal BAT displays a robust FGF21 expression pattern in pheochromocytoma patients and healthy controls." (PMID 35046901, 2021). "Our aim was to evaluate the relationship between the serum FGF21, and energy and glucose metabolism in 40 patients with pheochromocytoma/functional paraganglioma (PPGL), in comparison with 21 obese patients and 26 lean healthy controls." (PMID 30959789, 2019). "Analysis of visceral adipose tissue from the perirenal and omental regions in small samples of pheochromocytoma confirmed the presence of beige adipose tissue with significant expression of FGF21." (PMID 30959789, 2019). "To examine whether increased serum FGF21 level by pemafibrate administration directly acts on retinal cells, we used the in vitro culture system with pheochromocytoma (PC)12D neuronal cells." (PMID 32872333, 2020).
psoriasis (3 papers, 2019 to 2022). An autoimmune condition characterized by red, well-delineated plaques with silvery scales that are usually on the extensor surfaces and scalp. "Interestingly, FGF21, previously associated with overall metabolism, psoriasis, and embryonic development, has been proposed as an IR-alleviating factor by its downregulation during resistance training." (PMID 35454311, 2022). "In addition, the observed increase in FGF21, depending on the severity of psoriatic lesions, makes FGF21 an interesting marker combining the progression of psoriasis with an increased risk of developing metabolic disorders." (PMID 31847236, 2019). "Moreover, the possible contribution of FGF21 to the development and maintenance of inflammation are underlined by the correlation observed in our research between the concentration of FGF21 in patients with psoriasis and the CRP value." (PMID 31847236, 2019). "We were the first to evaluate the potential value of fibroblast growth factor 21 (FGF21) as one of the hepatokines in psoriasis." (PMID 32605214, 2020). "A significant decrease in FGF21 concentration after systemic treatment was observed in patients with severe psoriasis." (PMID 31847236, 2019). "Among patients with severe psoriasis, a similar trend of FGF21 before treatment was shown with HGB and RBCs concentrations, respectively p = 0.06 and p < 0.05." (PMID 31847236, 2019). "In the study, we observed positive correlation between FGF21 concentration and severity of psoriasis expressed through PASI on the border of statistical significance (p = 0.05)." (PMID 31847236, 2019). "The innovation of this study was also the assessment of the impact of systemic treatment used in psoriasis on the level of FGF21." (PMID 31847236, 2019). "FGF21 levels regarding psoriasis activity were significantly increased in all three subgroups compared to the controls (p < 0.05)." (PMID 31847236, 2019). "Nowadays, the use of fibroblast growth factors, namely 21 and 23 (FGF21, FGF23), are considered as a promising approach to assess the risk and diagnose the presence of psoriasis-related cardiometabolic abnormalities." (PMID 31847236, 2019). "Significantly higher levels of FGF21 in obese patients with psoriasis can result from both the accumulation of adipose tissue as well as that this increase can be enhanced by the immune-mediated inflammation in psoriasis." (PMID 31847236, 2019). "Thus, FGF21 can be not only a marker of coexisting metabolic disorders in psoriasis but also a marker of the progression and severity of skin lesions." (PMID 31847236, 2019). "Interestingly, in the group of patients with severe psoriasis, FGF21 level was relevantly high with statistical significance of p < 0.05." (PMID 31847236, 2019). "We also noticed a tendency to increase of FGF21 level within the psoriasis activity." (PMID 31847236, 2019). "The observed elevated concentration of FGF21 in patients with psoriasis also raises the question of whether psoriasis can be treated as a state of metabolic stress in the body, strong enough to trigger an increased production of FGF21." (PMID 31847236, 2019). "Hence, we can only point out the fact that increased FGF21 observed in all three groups of psoriatics, from mild to severe, suggests that systemic inflammation due to psoriasis favored FGF21 production." (PMID 31847236, 2019). "This leads to the question if psoriasis can also be considered as a state of metaflammation and if FGF21 could be a novel biomarker of psoriasis or progression of its comorbidities." (PMID 31847236, 2019). "Similarly, this inflammation and its severity may be responsible for elevated FGF21 concentrations among patients with a severe form of psoriasis, which we have presented in our research." (PMID 31847236, 2019). "Hence, elevated FGF21 levels in patients with psoriasis may be a good predictive marker of CMDs in psoriatics." (PMID 31847236, 2019).
psoriasis (continued). "Despite the existence of a broad spectrum of evidence, the exact role of FGF21 and FGF23 in psoriasis still requires further studies." (PMID 31847236, 2019). "In patients with moderate psoriasis, a significant (p < 0.05) negative correlation was demonstrated between the level of pre-treatment FGF21 and FGF23, and RBCs and HGB." (PMID 31847236, 2019). "Due to the lack of other studies among patients with psoriasis, we can only refer to publications highlighting the presumed involvement of FGF21 in the development of CMDs, and thus emphasize the possible association of psoriasis with the accelerated development of these complications." (PMID 31847236, 2019). "To date, there are no papers describing the concentrations of FGF21 in psoriasis." (PMID 31847236, 2019). "Moreover, our study showed a negative correlation of pre-treatment FGF21 levels with RBC count and HGB, mainly in patients with moderate to severe psoriasis." (PMID 31847236, 2019).
thyroid tumor (3 papers, 2019 to 2024). A benign or malignant neoplasm affecting the thyroid gland. "Previous studies have shown that FGF21 promotes aggressiveness in thyroid tumors by activating EMT signaling, ERK, and Akt pathways." (PMID 38238320, 2024). "To evaluate the role of FGF21 in tumor aggressiveness, we next investigated the effects of rFGF21 treatment on the migration and invasion of thyroid tumor cells." (PMID 31408968, 2019).
acute coronary syndrome (2 papers, 2018 to 2024). Signs and symptoms related to acute ischemia of the myocardium secondary to coronary artery disease. "Our study, which included patients with acute coronary syndromes, revealed that serum FGF21 levels were elevated compared to those reported in the literature for healthy subjects." (PMID 39194718, 2024). "This study investigated the relationship between FGF21 levels and clinical, biochemical, and echocardiographic parameters in patients with acute coronary syndromes (ACSs)." (PMID 39194718, 2024). "This study highlights the complex interplay between FGF21, BMI, and acute coronary syndromes." (PMID 39194718, 2024). "It indicated FGF21 resistance condition may explain the phenomenon of high serum FGF21 levels in pathological conditions of the heart, such as acute coronary syndrome." (PMID 30185439, 2018). "Therefore, high serum FGF21 levels in adverse metabolic dysregulation and acute coronary syndrome, such as UAP may be explained by FGF21 resistance conditions." (PMID 30185439, 2018).
adenoma (2 papers, 2018 to 2022). A neoplasm arising from the epithelium. "FGF21 can delay the conversion of adenomas to malignant tumors by regulating inflammation and lipid concentration in the liver." (PMID 36457562, 2022). "Overexpression of FGF21 likely delays the development of adenomas at an early stage of carcinogenesis." (PMID 36457562, 2022). "Associations of FGF-21 level with odds of advanced colorectal neoplasia were observed for both younger and older participants with borderline significance, while FGF-21 level was associated with odds of non-advanced adenoma for younger individuals." (PMID 30425347, 2018). "The levels between non-advanced adenoma and controls were mostly similar with exception to FGF-21 in the replication set." (PMID 30425347, 2018). "The AUC for non-advanced adenoma was similar to that of advanced colorectal neoplasia, though FGF-21 showed slightly higher sensitivity to detect advanced colorectal neoplasia than non-advanced adenoma." (PMID 30425347, 2018).
AIDS (2 papers, 2021 to 2022). A syndrome resulting from the acquired deficiency of cellular immunity caused by the human immunodeficiency virus (HIV). "Previous data have shown that non-AIDS comorbidities in PLWH are known to be influenced by metabolic, inflammatory, and viral factors; thus we tested markers related to such aspects, including GDF-15, suPAR, FGF-21, GLP-2, CRP, anti-CMV IgGs, and anti-EBV IgGs." (PMID 36093162, 2022).
allergic asthma (2 papers, 2020). A asthma with a basis in a pathological type I hypersensitivity reaction. "Young adults with allergic asthma show increased number of circulating mast cell progenitors related to female gender, high levels of fibroblast growth factor 21 (FGF-21) and reduced lung function." (PMID 32102344, 2020). "Thus, this modulatory action of EGF and FGF21 could be interpreted as harmful, however, it is possible that it is a way to control the large amounts of Th1 and Th2 cytokines that activated NKT can produce, and may contribute, for example, to the development of IgE-mediated allergic asthma." (PMID 32599899, 2020).
Atrophy (2 papers, 2021 to 2025). Any weakening or degeneration, especially through lack of use. "Collectively, these findings suggest that muscular FGF21 may contribute to the progression of neurogenic muscle atrophy." (PMID 40998017, 2025).
breast tumor (2 papers, 2013 to 2024). "NAMPT as a downstream target of FGFR4 deficiency and FGF21 elevation is highly expressed in breast tumor foci but attenuated by the FGFR4 deficiency." (PMID 24279986, 2013). "Thus both adiponectin of systemic origin from distal fat depots and from local breast adipocytes under the control of FGF21 could play a major role directly on breast tumor epithelial cells and their microenvironment." (PMID 24279986, 2013). "Furthermore, our study provided potential new targets, such as FGF21, adiponectin, NAMPT and Acly, for suppressing breast tumor malignancy concurrently with inhibition of FGFR." (PMID 24279986, 2013). "However, the expression patterns of FGF21 in breast tumor tissues remain unclear, and the impact of FGF21 on tumor growth and progression has not been reported." (PMID 38238320, 2024).
cardiac arrest (2 papers, 2021 to 2023). Cessation of breathing and/or cardiac function. "Oxidative metabolism is disturbed in tissues during cardiac arrest and we have previously shown in the COMACARE cohort that FGF‐21, a marker of mitochondrial and cellular stress is associated with outcome after cardiac arrest." (PMID 36053856, 2023).